ALKBH3 (alkB homolog 3, alpha-ketoglutarate dependent dioxygenase)
Description:
Dioxygenase that mediates demethylation of DNA and RNA containing 1-methyladenosine (m1A). Repairs alkylated DNA containing 1-methyladenosine (m1A) and 3-methylcytosine (m3C) by oxidative demethylation. Has a strong preference for single-stranded DNA. Able to process alkylated m3C within double-stranded regions via its interaction with ASCC3, which promotes DNA unwinding to generate single-stranded substrate needed for ALKBH3. Can repair exocyclic 3,N4-ethenocytosine adducs in single-stranded DNA. Also acts on RNA. Demethylates N(1)- methyladenosine (m1A) RNA, an epigenetic internal modification of messenger RNAs (mRNAs) highly enriched within 5'-untranslated regions (UTRs) and in the vicinity of start codons. Requires molecular oxygen, alpha-ketoglutarate and iron.
Synonyms: hABH3; ABH3; DEPC1; DEPC-1; PCA1
Tractability: Small molecule: a structure with a bound ligand is known; a high-quality ligand is known; it has a binding pocket of medium quality. PROTAC: UniProt records ubiquitination sites on it; ubiquitination databases record sites on it; its protein half-life has been measured; a small molecule that binds it is known.
Target class: Enzyme; Oxidoreductase
Gene: Protein-coding gene on chromosome 11 (43,880,811 to 43,920,274, forward strand). Ensembl gene ENSG00000166199.
Subcellular location: Nucleus; Cytoplasm
Subcellular location (Human Protein Atlas): Nucleoplasm; Mitochondria
Pathways (Reactome):
DNA Repair: ALKBH3 mediated reversal of alkylation damage
Gene Ontology:
Molecular function: broad specificity oxidative DNA demethylase activity; ferrous iron binding; mRNA N1-methyladenosine dioxygenase activity; oxidative RNA demethylase activity; protein binding; dioxygenase activity
Biological process: cell population proliferation; DNA alkylation repair; negative regulation of cytoplasmic translation; DNA repair
Cellular component: cytoplasm; nucleoplasm; nucleus
Genetic constraint (gnomAD): Loss-of-function variants: 42 observed, 37.88 expected, observed/expected ratio (o/e) 1.11, 90% interval 0.87 to 1.43. The upper end of that interval is the gene's LOEUF score, 1.43, which puts it in group 5 of 6, group 1 being the genes least tolerant of losing a copy. Missense variants: 317 observed, 322.1 expected, observed/expected ratio (o/e) 0.98, 90% interval 0.9 to 1.08. Synonymous variants: 90 observed, 108.86 expected, observed/expected ratio (o/e) 0.83, 90% interval 0.7 to 0.99.
Homologues: Orthologues: chimpanzee ALKBH3 (100% identical), macaque ALKBH3 (98% identical), pig ALKBH3 (90% identical), guinea pig ALKBH3 (86% identical), rat Alkbh3 (86% identical), mouse Alkbh3 (84% identical), dog ALKBH3 (80% identical), rabbit ALKBH3 (70% identical), tropical clawed frog alkbh3 (61% identical), zebrafish alkbh3 (53% identical).
Diseases named in the same sentence as ALKBH3 in open-access papers:
ALKBH3 is named in the same sentence as 56 diseases in open-access papers, as found by Europe PMC text mining. Sharing a sentence is not in itself a finding about the gene and the disease. The quoted sentences say what the papers report.
prostate carcinoma (20 papers, 2011 to 2025). A carcinoma that arises from epithelial cells of the prostate gland. "ALKBH3, a demethylase of m1A, is also a potential diagnostic marker for prostate cancer.ALKBH3 is highly expressed in prostate cancer and correlates with disease progression and prognosis." (PMID 38117350, 2023). "Recently, it was elegantly shown that ALKBH3 is associated with the helicase ASCC3 to demethylate endogenously methylated 3-meC in ssDNA in prostate cancer cells." (PMID 28205560, 2017). "ALKBH3 is also linked to prostate cancer and an alternate name is prostate cancer-1 (PCA-1)." (PMID 35582025, 2021). "Moreover, upregulation of ALKBH3 is implicated in the development of non-small cell lung cancer and prostate cancer." (PMID 33302959, 2020). "Subsequently, the oncogenic role of ALKBH3 and m1A demethylation of mRNA has also been found in urothelial cancers, prostate cancer, breast cancer, colorectal, and NSCLC." (PMID 34638933, 2021). "Other members of the ALKBH family, such as ALKBH3, are essential for cancer progression and present themselves as potential targets for effective therapy in prostate cancer." (PMID 33897761, 2021). "Studies showed that prostate cancers overexpress ALKBH3 and noted that overexpression is related to the metastatic cancers with poor prognosis." (PMID 34561912, 2021). "The specific m1A demethylase ALKBH3 which is originally known as prostate cancer antigen-1 (PCA-1) is present in high abundance in prostate cancer." (PMID 32194861, 2020). "Knockdown of ALKBH3 was found to decrease the proliferation of prostate cancer cell proliferation and tumor growth in vivo." (PMID 32194861, 2020). "Significantly, the combination treatment of MMS and BPTES resulted in a striking synergistic killing of PC3 cells, which have high expression levels of ALKBH3 compared to other prostate cancer cell lines." (PMID 29107960, 2017). "Our previous work showed that ALKBH3 depletion in PC3 prostate cancer cells increases global 3-meC levels and induces H2A.X phosphorylation as well as 53BP1 foci formation, demonstrating the occurrence of systemic DNA damage." (PMID 26221185, 2015). "Moreover, ALKBH3 is significantly over-expressed in prostate cancer and is also known as prostate cancer antigen-1 (PCA-1)." (PMID 28231280, 2017). "ALKBH3 overexpression is found in prostate cancer and other cancer types." (PMID 28679371, 2017). "Moreover, ALKBH3 overexpression promotes alkylation damage resistance in prostate cancer and apoptotic resistance in pancreatic cancer." (PMID 29107960, 2017). "We have demonstrated for the first time that a novel human AlkB homologue, ALKBH3, contributes to prostate cancer development, but its clinical and biological roles in lung cancer remain unclear." (PMID 21285982, 2011). "Thus, targeting ALKBH3 is a potential way to use alkylating agent therapy for prostate cancer." (PMID 35582025, 2021). "Compared with normal tissues, ALKBH3 is highly expressed in pancreatic, lung, and urothelial cancers, and is evenly identified as the high-grade prostate cancer marker, implying that ALKBH3 may function in the tumorigenesis process and would be helpful for the early diagnosis." (PMID 34272618, 2021). "The m1A demethylase ALKBH3, also known as prostate cancer antigen 1 (PCA-1), in addition to being exceptionally abundant in prostate cancer, the oncogenic role of m1A demethylation has been found in colon, breast, and lung cancers." (PMID 35464855, 2022). "The specific m1A demethylase ALKBH3, originally known as the prostate cancer antigen-1 (PCA-1), is highly abundant in prostate cancer." (PMID 34638933, 2021). "In parental PC-3 prostate cancer cells, a similar staining pattern of ASCC3 and ALKBH3 was observed as in HeLa, except that more distinct cytoplasmic P-bodies were present in the untreated PC-3 cells." (PMID 34217309, 2021).
prostate carcinoma (continued). "To further elucidate the function of ALKBH3 in cancer, we performed ChIP-seq to investigate the genomic binding pattern of endogenous ALKBH3 in PC3 prostate cancer cells coupled with microarray experiments to examine the expression effects of ALKBH3 depletion." (PMID 26221185, 2015). "A motif search identified the ETS transcription factor binding motif to be most significantly enriched, suggesting that genes occupied by ALKBH3 are possibly activated by one or several ETS factors, which are often over-expressed in prostate cancer." (PMID 26221185, 2015). "In order to gain further insights into the function of ALKBH3 particular in cancer, we applied genome wide approaches using PC3 prostate cancer cells as a model." (PMID 26221185, 2015). "Moreover, our study presents evidence that USP7 stabilizes the demethylation repair proteins ALKBH2 and ALKBH3 in GBM cells, expanding upon previous observations in prostate cancer cells." (PMID 40835840, 2025). "ALKBH3, which is prostate carcinoma antigen-1 (PCA-1), exhibits high expression in several cancers of humans and facilitates angiogenesis and apoptotic resistance in pancreatic and prostate cancer." (PMID 34188972, 2021). "We previously reported that ALKBH3 (originally named as prostate cancer antigen-1 (PCA-1)) is highly expressed in prostate cancer, and that knockdown of this homolog in prostate cancer cell lines significantly inhibits in vitro cell growth and in vivo tumor growth in a xenograft model." (PMID 28205560, 2017).
breast carcinoma (7 papers, 2016 to 2024). "High expression of m1A-related regulators (m1A writer TRMT6, TRMT61A, and eraser ALKBH3) was associated with poor prognosis in several cancers, including hepatocellular carcinoma, colon cancer, glioma, breast cancer, and ovarian cancer." (PMID 38655053, 2024). "In a similar manner, high levels of ALKBH3 associated with the poor outcome of patients with pancreatic cancer and renal cell carcinoma, while the opposite was observed in breast cancer, lung adenocarcinoma and Hodgkin lymphoma." (PMID 38672281, 2024). "Thirdly, the majority of the CpGs identified as differentially methylated are also found significantly associated with down-regulation of ALKBH3 mRNA levels in breast cancers." (PMID 28679371, 2017). "We further show that increasingly higher degree of ALKBH3 promoter methylation is associated with reduced breast-cancer specific survival times in patients." (PMID 28679371, 2017). "As the data shown, the OS of breast cancer patient was significant difference when gene expression was changed in ALKBH3 (p=0.00063), ALKBH4 (p=0.013), ALKBH7 (p=0.0025), ALKBH8 (p=0.00013) and FTO (p=0.045)." (PMID 35980268, 2022). "This is of particular importance since both ALKBH2 and ALKBH3 have been proposed as tumor suppressors, being silenced in various tumors, including gastric and breast cancer." (PMID 34723799, 2021). "In breast cancer cell lines, there are also differences in the level of ALKBH3, with certain lines (e.g., MCF-7) having relatively high levels of ALKBH3 and other cell lines (e.g., Bt-474) having relatively low levels of ALKBH3." (PMID 35582025, 2021). "We identified ALKBH3 promoter methylation in two of the seven breast cancer cell lines, i.e. in CAMA-1 and Bt-474." (PMID 28679371, 2017). "While our data suggest that ALKBH3 has tumor suppressor properties in breast cancer, other research has shown ALKBH3 overexpression in various cancer types." (PMID 28679371, 2017). "In our cohort of 265 primary breast cancer, we found 72 cases showing aberrantly high CpG promoter methylation over the ALKBH3 promoter (27%; 72 out of 265)." (PMID 28679371, 2017). "Our results support this notion by identifying the ALKBH3 gene as a novel addition to the catalogue of DNA repair genes found inactivated in breast cancer." (PMID 28679371, 2017). "We propose here that the ALKBH3 gene is a novel addition to the catalogue of DNA repair genes found inactivated in breast cancer." (PMID 28679371, 2017). "The analysis of these datasets consistently identify aberrant CpG methylation over the ALKBH3 gene promoter in breast cancers." (PMID 28679371, 2017). "In our cohort, clinically relevant ALKBH3 promoter methylation occurs in at least 5% of all breast cancers and, although independent cohorts will be needed for confirmation, this event appears to be associated with highly aggressive disease behaviour." (PMID 28679371, 2017). "Using this definition, we report the incidence of ALKBH3 promoter methylation at approximately 5% in our cohort (13 out of 265 primary breast cancers)." (PMID 28679371, 2017). "The ALKBH3 gene is therefore a novel addition to the catalogue of DNA repair genes found inactivated in breast cancer." (PMID 28679371, 2017). "Secondly, significantly lower expression levels of ALKBH3 mRNA were seen in breast cancers compared with normal breast tissue samples." (PMID 28679371, 2017). "ALKBH3 is a novel addition to the catalogue of DNA repair genes found inactivated in breast cancer." (PMID 28679371, 2017). "With compared the expression of ALKBH family members in breast cancer and normal samples, the up-regulation was ALKBH1, ALKBH2, ALKBH4, ALKBH6, ALKBH7, and others such as ALKBH3, ALKBH8, FTO was down-regulation." (PMID 35980268, 2022). "By making use of methylome data for breast cancers and normal breast tissues, we specifically asked whether aberrant CpG methylation events are found over the promoter region of either ALKBH2 or ALKBH3." (PMID 28679371, 2017).
breast carcinoma (continued). "In this study, we demonstrate that the ALKBH3 gene, not ALKBH2, is found recurrently silenced in breast cancer by epigenetic events which, furthermore, defines a group of patients with dramatically reduced survival." (PMID 28679371, 2017). "The ALKBH3 gene, but not ALKBH2, undergoes CpG promoter methylation and transcriptional silencing in breast cancer." (PMID 28679371, 2017).
Hodgkins lymphoma (6 papers, 2022 to 2024). A heterogeneous group of malignant lymphoid neoplasms of B-cell origin characterized histologically by the presence of Hodgkin and Reed-Sternberg (HRS) cells in the vast majority of cases. "Moreover, ALKBH3 loss induces m1A hypermethylation of the transcriptome in Hodgkin lymphoma, which is associated with poor clinical outcome." (PMID 38118002, 2024). "Hodgkin lymphoma cells were found to have ALKBH3 hypermethylation of the promoter CpG island and its transcriptional silencing, which has also been linked to poor clinical outcomes in Hodgkin lymphoma patients." (PMID 39459530, 2024). "In Hodgkin’s lymphoma, COL1A1 overexpression is associated with epigenetic silencing of the RNA demethylase ALKBH3 and reduced survival." (PMID 36873459, 2022). "Furthermore, ALKBH3 promoter CpG island hypermethylation and transcriptional silencing were found in Hodgkin lymphoma cells, which were identified as a potential prognostic biomarker associated with poor clinical outcomes in patients with Hodgkin lymphoma." (PMID 35627295, 2022).
pancreatic cancer (6 papers, 2017 to 2024). "ALKBH3 upregulation has been associated with poorer prognostic outcomes in several cancers, including non-small-cell lung cancer, pancreatic cancer, renal cell carcinoma, and hepatocellular carcinoma." (PMID 39200230, 2024). "The increased expression of ALKBH3 in some pancreatic cancers is associated with poor outcomes and reduced survival in patients, but it is unclear if high ALKBH3 levels are also associated with resistance to treatment with alkylating agents in those patients." (PMID 35582025, 2021). "Previous studies in pancreatic cancer and in head and neck squamous cell carcinoma found that ALKBH3 was overexpressed in tumour compared to the healthy tissues." (PMID 38672281, 2024). "Studies have also reported that the high expression of ALKBH3 was positively correlated with the advanced tumor stage of pancreatic cancer, which indicates that m1A does have clear prognostic value in pancreatic cancer." (PMID 33779693, 2021).
gastric cancer (5 papers, 2024 to 2026). A primary or metastatic malignant neoplasm involving the stomach. "Notably, ALKBH3 functions as a tumor suppressor in gastric cancer, and its expression is closely associated with PUS7 levels in tumor tissues." (PMID 39737343, 2024). "For instance, PUS7-dependent pseudouridylation of ALKBH3 mRNA enhances its translation efficiency, inhibiting gastric cancer cell proliferation and tumor growth." (PMID 40260225, 2025). "Our findings show that ALKBH3 acts as a tumour suppressor in gastric cancer by inhibiting cell proliferation and tumour growth." (PMID 39175405, 2024). "PUS7‐dependent pseudouridylation of ALKBH3 mRNA enhances its translation, thereby suppressing gastric cancer progression." (PMID 39175405, 2024). "Taken together, these results suggest that ALKBH3 functions as a tumour suppressor gene in gastric cancer." (PMID 39175405, 2024). "This study investigates the impact of pseudouridine synthase 7 (PUS7)‐mediated pseudouridylation of Alpha‐ketoglutarate‐dependent Dioxygenase alkB Homolog 3 (ALKBH3) mRNA in gastric cancer." (PMID 39175405, 2024). "PUS7 and ALKBH3 exert an inhibitory effect on the proliferation and tumour growth of gastric cancer cells." (PMID 39175405, 2024). "Our study demonstrates that the expression levels of both PUS7 and ALKBH3 are significantly diminished in gastric cancer tissues." (PMID 39175405, 2024). "Our study sheds new light on this issue by demonstrating that PUS7‐dependent pseudouridylation of ALKBH3 mRNA increases the translation efficiency of ALKBH3 mRNA and subsequently suppresses gastric cancer cell proliferation and tumour growth." (PMID 39175405, 2024). "The expression levels of PUS7 and ALKBH3 are significantly correlated in gastric tumors, positioning them as potential prognostic indicators and therapeutic targets for patients with gastric cancer." (PMID 39737343, 2024). "Here, our study reveals that the expression of PUS7 and ALKBH3 are both significantly reduced in gastric cancer tissues." (PMID 39175405, 2024). "Importantly, ALKBH3 functions as a tumour suppressor in gastric cancer, with its expression closely correlated with PUS7 levels in tumour tissues." (PMID 39175405, 2024). "The expression levels of PUS7 and ALKBH3 are significantly correlated in gastric tumours, which may be potential prognostic predictors and therapeutic targets for patients with gastric cancer." (PMID 39175405, 2024). "PUS7 and ALKBH3 are characterized as novel tumour suppressors in gastric cancer." (PMID 39175405, 2024). "Conversely, ALKBH2, ALKBH3, ALKBH5, ALKBH6, and ALKBH7 showed low expression in gastric cancer tissues." (PMID 38902235, 2024). "While studying the effect of PUS7 on gastric cancer cells, we made the serendipitous observation that knockdown of PUS7 dramatically reduced the expression of the demethylase ALKBH3 in MKN45 cells." (PMID 39175405, 2024). "Thus, we identify PUS7 and ALKBH3 as novel gastric cancer suppressor genes, and our findings suggest that PUS7‐dependent pseudouridylation of ALKBH3 mRNA inhibits gastric carcinogenesis." (PMID 39175405, 2024). "However, the role of ALKBH3 in gastric cancer progression has not been reported." (PMID 39175405, 2024).
lung carcinoma (5 papers, 2011 to 2025). "In contrast, ALKBH3 levels were lower in tumour compared to healthy tissues in other types of cancer, such as breast and lung carcinomas." (PMID 38672281, 2024). "We have since found novel biological roles for ALKBH3 in human lung cancers, particularly in adenocarcinoma." (PMID 21285982, 2011). "It was reported that ASCC3 could collaborate with ALKBH3 to repair DNA alkylation damage in prostate and lung cancer cells that sustained high levels of ALKBH3 expression." (PMID 40067902, 2025). "Additionally, the eraser ALKBH3 is overexpressed in lung cancer (LC) and promotes cancer cell proliferation, migration, and invasion by inducing tRNA-derived small RNAs." (PMID 41244907, 2025). "The presence of ALKBH3 at some of those gene promoters was confirmed in NCI-H23 lung cancer cells, suggesting that the genomic binding pattern of ALKBH3 as well as the occurrence of hyperactive promoters is similar in ALKBH3 over-expressing cancer cells." (PMID 26221185, 2015). "ALKBH3 gene silencing inhibits cancer cell survival, and targeted downregulation, as was carried out in our in vivo study by injection of a siRNA and atelocollagen cocktail, could be a novel clinical tool for lung cancer therapy." (PMID 21285982, 2011). "This is supported by comprehensive biochemical studies on ALKBH3 ubiquitination, which found that ALKBH3 mRNA levels did not correlate well with ALKBH3 protein expression in prostate, breast or lung carcinoma cell lines." (PMID 38672281, 2024).